ALG1L2 (ALG1 chitobiosyldiphosphodolichol beta-mannosyltransferase like 2)
Description:
Putative glycosyltransferase.
Tractability: PROTAC: ubiquitination databases record sites on it.
Gene: Protein-coding gene on chromosome 3 (130,081,831 to 130,113,227, forward strand). Ensembl gene ENSG00000251287.
Subcellular location (Human Protein Atlas): Endoplasmic reticulum; Nucleoli fibrillar center
Gene Ontology:
Molecular function: mannosyltransferase activity; glycosyltransferase activity
Genetic constraint (gnomAD): Loss-of-function variants: 32 observed, 26.7 expected, observed/expected ratio (o/e) 1.2, 90% interval 0.9 to 1.61. The upper end of that interval is the gene's LOEUF score, 1.61, which puts it in group 6 of 6, group 1 being the genes least tolerant of losing a copy. Missense variants: 318 observed, 261 expected, observed/expected ratio (o/e) 1.22, 90% interval 1.11 to 1.34. Synonymous variants: 110 observed, 105.05 expected, observed/expected ratio (o/e) 1.05, 90% interval 0.9 to 1.23.
Homologues: Orthologues: dog ALG1 (75% identical), rat Alg1 (74% identical), mouse Alg1 (74% identical), zebrafish alg1 (59% identical), tropical clawed frog alg1 (59% identical), Drosophila melanogaster Alg1 (44% identical), Caenorhabditis elegans algn-1 (38% identical). Paralogues in human: ALG1 (87% identical).
Diseases named in the same sentence as ALG1L2 in open-access papers:
ALG1L2 is named in the same sentence as 2 diseases in open-access papers, as found by Europe PMC text mining. Sharing a sentence is not in itself a finding about the gene and the disease. The quoted sentences say what the papers report.
proctitis (1 paper, 2020). An inflammatory process affecting the anus. "The copy number analysis identified seven regions associated with proctitis, one of which (ALG1L2) was also associated with proctitis based on transcriptomic profiles in the whole-blood tissue." (PMID 33008348, 2020). "The ALG1L2 mapped to the significant CNV region on chr3:129690192–129,896,364 (along with TRH and FAM86HP) was also found to be associated with proctitis in the transcriptomic analysis of whole-blood tissue, while the other two genes (TRH & FAM86HP) were not predicted in either of the two tissues." (PMID 33008348, 2020).
tumor (2 papers, 2014 to 2023). "The Wilcoxon Rank Sum test revealed that ALG1L2, B3GNT3, and B3GNT8 were expressed at higher levels in tumor tissues, while HS6ST3 and ST8SIA5 were expressed at lower levels in tumor tissues (all P < 0.01)." (PMID 38097951, 2023).